PON3 (paraoxonase 3)
Diseases named in the same sentence as PON3 in open-access papers (continued):
Sharing a sentence is not in itself a finding about the gene and the disease.
depressive disorder (3 papers, 2022 to 2023). A melancholy feeling of sadness and despair. "mRNA expression of the PON1, PON2 and PON3 genes was slightly higher in patients with depressive disorders than in the control group, however, this relationship was not statistically significant." (PMID 35743392, 2022). "mRNA expression of PON1, PON2 and PON3 genes was slightly higher in patients with depressive disorders than in the control group, however this relationship was not statistically significant (PON1 p = 0.5895, PON2 p = 0.1342 and PON3 p = 0.2818)." (PMID 35743392, 2022).
gallstones (3 papers, 2016 to 2025). Solid crystalline precipitates in the biliary tract, usually formed in the gallbladder, resulting in the condition of cholelithiasis. "Disrupting mitochondrial function by knocking out paraoxonase 3 gene (Pon3) causes significant increases of mouse plasma and hepatic cholesterol levels, hepatotoxicity markers in circulation, gallstone weight, and mortality." (PMID 27462273, 2016).
heart failure (3 papers, 2021 to 2023). Inability of the heart to pump blood at an adequate rate to meet tissue metabolic requirements. "The knowledge of paraoxonase 3 in human is limited but it has been found associated with iron deficiency in patients with worsening heart failure." (PMID 35727504, 2023). "In contrast, expression levels of paraoxonase enzymes 1-3 (Pon1, Pon2, Pon3), which could detoxify oxidated lipids and alleviate angiotensin-II-induced heart failure, were unaltered in Tg-SCD hearts (Figure A6a–c)." (PMID 34576047, 2021).
Hypertension (3 papers, 2015 to 2024). The presence of chronic increased pressure in the systemic arterial system. "Among these 27 validated proteins, 26 were positively associated with hypertension or SBP, while PON3 (paraoxonase) demonstrated an inverse association." (PMID 38445514, 2024). "We then examined whether serum PON3 concentration correlated with commonly identified predictors of arylesterase activity, such as age, sex, and hypertension (correlations between arylesterase activity and these variables were also observed in this study but are not presented herein)." (PMID 39456469, 2024).
melanoma (3 papers, 2017 to 2021). A malignant, usually aggressive tumor composed of atypical, neoplastic melanocytes. "Of these, PON3, CD14 and RAP1B were evaluated for their association with survival in the primary melanoma sample data set of the TCGA." (PMID 34439311, 2021). "Here, we identified, and validated in an independent validation cohort, three genes (MEOX2, OLIG3, and PON3) for which the degree of DNA methylation can predict the prognosis of melanoma patients." (PMID 28578692, 2017). "Differentially methylated genes included three non-melanoma related genes (MEOX2, OLIG3, PON3), but previously associated with DNA methylation and cancer prognosis in other pathologies." (PMID 28578692, 2017). "Moreover, DNA methylation of PON3 was predictive for overall survival in The Cancer Genome Atlas cohort of 223 patients with melanoma." (PMID 28578692, 2017). "By proteomics we identified five proteins in plasma CD81sEV that were differentially expressed between HD and stage II (APOA5, PON1, PON3 and CD14) and between HD and stage III–IV, advanced stage melanoma, (RAP1B)." (PMID 34439311, 2021). "To evaluate the relationship among PON3, CD14 and RAP1B and prognoses of melanoma patients, we conducted Kaplan–Meier survival analysis according to gene expression data of PM." (PMID 34439311, 2021). "To explore whether the identified proteins, APOA5, PON1, PON3, CD14 and RAP1B, could be of any clinical relevance, we evaluated their expression in silico in relation to the available clinical information in the TCGA dataset of primary melanoma samples (PM, n = 80)." (PMID 34439311, 2021).
pancreatic cancer (3 papers, 2020 to 2024). "Studies have shown that like PON2, PON3 has an oncogenic role and that PON3 is expressed in tumors of the pancreas, lung, bladder, ovary, kidney, and prostate." (PMID 32549522, 2020).
prostate carcinoma (3 papers, 2017 to 2024). A carcinoma that arises from epithelial cells of the prostate gland. "PON3 hypermethylation could also serve as a mechanism for explaining the association between smoking and adverse prostate cancer outcomes." (PMID 35326240, 2022).
cerebral infarction (2 papers, 2023 to 2025). An ischemic condition of the brain, producing a persistent focal neurological deficit in the area of distribution of the cerebral arteries. "Regression analyses revealed that heightened PON-3 methylation was associated with a protective role for cerebral infarction." (PMID 37108044, 2023). "One study investigated the relationship between the promoter methylator of the PON-3 gene and the risk of cerebral infarction." (PMID 37108044, 2023). "Mutations in the PON-3 gene are closely related to cerebral infarction risk." (PMID 37108044, 2023). "The promoter methylation levels of PON-3 were analyzed in 152 cerebral infarction case samples and 152 healthy control samples." (PMID 37108044, 2023). "Other studies have also indicated that PON-3 dysfunction contributes to neurotoxicity and cerebral infarction." (PMID 37108044, 2023). "Researchers observeds that PON-3 methylation was significantly lower in the cerebral infarction group compared to the control." (PMID 37108044, 2023).
chordoma (2 papers, 2017 to 2018). Chordomas are rare malignant tumors arising from embryonic remnants of the notochord in axial skeleton. "Previous studies also showed that PON3 is hypermethylated in colorectal cancer and chordomas." (PMID 30386177, 2018).
chronic kidney disease (2 papers, 2022 to 2023). Impairment of the renal function secondary to chronic kidney damage persisting for three or more months. "Here, we examine the role of PON3 in regulating CTS levels in a rat model of chronic kidney diseases (CKD)." (PMID 36362352, 2022).
Cirrhosis (2 papers, 2016). A chronic disorder of the liver in which liver tissue becomes scarred and is partially replaced by regenerative nodules and fibrotic tissue resulting in loss of liver function. "Further analyses of our own previously constructed microarray data (GSE54238) showed that PON3 was progressively downregulated as normal liver develops into chronic hepatitis, cirrhosis, early-stage HCC, and advanced HCC." (PMID 27661119, 2016).
colorectal cancer (2 papers, 2018 to 2021). A primary or metastatic malignant neoplasm that affects the colon or rectum. "In the screening setting, a multi-marker panel containing HP, LRG1 and PON3 had an AUC of 0.65 for detection of advanced adenomas and another panel, optimized for detecting colorectal cancer, reached an AUC of 0.79." (PMID 34503217, 2021).
endothelial dysfunction (2 papers, 2019 to 2025). In vascular diseases, endothelial dysfunction is a systemic pathological state of the endothelium (the inner lining of blood vessels) and can be broadly defined as an imbalance between vasodilating and vasoconstricting substances produced by (or acting on) the endothelium. "Notably, IL-6 and CUB domain-containing protein 1 (CDCP-1) correlated with both endothelial dysfunction and the presence of plaques, whereas paraoxonase 3 (PON-3) showed protective, anti-atherogenic properties." (PMID 41427121, 2025). "PON3 codes for an enzyme that associates with HDL and prevents oxidation of LDL which otherwise would result in endothelial dysfunction." (PMID 30838035, 2019).
Insulin resistance (2 papers, 2021 to 2024). Increased resistance towards insulin, that is, diminished effectiveness of insulin in reducing blood glucose levels. "Following liraglutide (glucagon-like peptide-1 analog known to reduce BMI and insulin resistance, Novo Nordisk) treatment and improvement of metabolic features, PON3 levels increased in this model." (PMID 39589852, 2024).
oral squamous cell carcinoma (2 papers, 2022 to 2024). "PON3 regulates cell proliferation, cell cycle, migration and invasion in oral squamous cell carcinoma via the PI3K/Akt pathway." (PMID 36499383, 2022).
systemic lupus erythematosus (2 papers, 2019 to 2025). An autoimmune multi-organ disease typically associated with vasculopathy and autoantibody production. "Additionally, an inverse correlation between PON3 concentration in HDL particles and body mass index was observed in patients with systemic lupus erythematosus, suggesting a role in adiposity regulation." (PMID 41303537, 2025).
type 2 diabetes (2 papers, 2019 to 2022). "A risk-decreasing effect on type 2 diabetes of raised PON-3 levels using the inverse variance-weighted method (p = 3.0 × 104) was cast in doubt by evidence of heterogeneity (p = 3.1 × 10−2) and horizontal pleiotropy in MR Egger (p = 0.033)." (PMID 31446444, 2019). "In patients with type 2 diabetes mellitus (T2DM), the severity of CAD is associated with an increase in apolA-I glycation and decrease in HDL-associated PON1 and PON3 activity." (PMID 35326240, 2022).
age (1 paper, 2024). A temporal measurement of the time period elapsed since an identifiable point in the life cycle of an organism. "Ultimately, we propose PON3 as a potential biomarker for age-related sarcopenia." (PMID 39725826, 2024).
amyotrophic lateral sclerosis (1 paper, 2025). Amyotrophic lateral sclerosis (ALS) is a neurodegenerative disease characterized by progressive muscular paralysis reflecting degeneration of motor neurons in the primary motor cortex, corticospinal tracts, brainstem and spinal cord. "Furthermore, the loss of Pon3's antioxidant function leads to lipid peroxidation that damages neurons, ultimately exacerbating amyotrophic lateral sclerosis." (PMID 40884250, 2025).
Arthritis (1 paper, 2020). Inflammation of a joint. "Levels of PON2 and PON3 proteins were significantly higher in livers from PON1KO mice compared to WT controls following arthritis induction." (PMID 33033318, 2020).
benign prostatic hyperplasia (1 paper, 2020). A non-cancerous nodular enlargement of the prostate gland. "The present study investigated differences in PON1 and PON3 activities and serum MDA levels and lipid profile levels between patients with Pca, patients with benign prostatic hyperplasia (BPH) having previously undergone RALRP, and a control group." (PMID 32549522, 2020).
Brain atrophy (1 paper, 2024). Partial or complete wasting (loss) of brain tissue that was once present. "Interestingly, lower arylesterase activity, but not PON3, was found in subjects with brain atrophy compared to those not presenting this AD pathological trait (p < 0.01)." (PMID 39456469, 2024).
breast carcinoma (1 paper, 2024). "We used the XGBoost machine learning model and AUC value to screen out the optimal combinations of variables for breast cancer diagnosis from a variety of differential proteins: PON3, IGLV3‐10, and IGHV3‐73." (PMID 39641443, 2024). "In this study, it was found that the expression of PON3 protein in the plasma of breast cancer patients was reduced, which was consistent with the previous results of breast cancer proteomics." (PMID 39641443, 2024). "The findings of this study suggest that the combination of PON3, IGLV3‐10, and IGHV3‐73 proteins in a model demonstrates a significant ability to differentiate between individuals with breast cancer and HC." (PMID 39641443, 2024).
cardiac amyloidosis (1 paper, 2025). Cardiac amyloidosis is a condition whereby cardiac tissue is infiltrated by amyloid fibrils. "PON3, SIGLEC1, and IL-6 demonstrated a statistically non-significant trend of a weak-to-moderate association with MACE in cardiac amyloidosis." (PMID 41007815, 2025).
cardiac hypertrophy (1 paper, 2022). "However in a preclinical study, the paraoxonase gene cluster has been shown to be protective against cardiac hypertrophy, with PON3 becoming upregulated in heart muscle in the course of remodelling." (PMID 35181700, 2022).
coronary atherosclerosis (1 paper, 2015). Atherosclerosis of the coronary vasculature. "At middle and particularly high tertile of apoA-I glycation, patients with low levels of HDL-associated activities of PON1 and PON3 had approximately 2 to 2.5 fold increased risk for severe coronary atherosclerosis." (PMID 25964115, 2015).
delirium (1 paper, 2026). A disorder characterized by confusion; inattentiveness; disorientation; illusions; hallucinations; agitation; and in some instances autonomic nervous system overactivity. "Our druggability assessment found PON3 to be a notable drug target for delirium." (PMID 41286463, 2026). "In our analysis, increased PON3 plasma level was found to have protective effect against delirium." (PMID 41286463, 2026).
hypertensive renal disease (1 paper, 2022). "Ten-week-old Dahl salt-sensitive wild type (SS-WT) and Dahl salt-sensitive PON3 knockout (SS-PON3 KO) rats were maintained on a high-salt diet (8% NaCl) for 8 weeks to initiate salt-sensitive hypertensive renal disease characteristic of this model." (PMID 36362352, 2022). "Our results suggest a potential new role for PON3 in regulating CTS levels in the setting of hypertensive renal disease." (PMID 36362352, 2022).
liver cancer (1 paper, 2016). An epithelial or non-epithelial malignant neoplasm that arises from the liver. "All these findings suggest that PON3 is more hepatoprotective, and may suppress the progression of liver cancer." (PMID 27661119, 2016).
liver fibrosis (1 paper, 2024). "Lastly, some (borderline) significant associations for rare PON3 variants associated with liver fibrosis stage and lobular inflammation are described for certain burden tests." (PMID 39334710, 2024).
lung carcinoma (1 paper, 2024). "The genes Fubp1, Cox6b1, Pon3, Iars2, Ctsd, and Akr1b1 have been previously shown to promote lung cancer proliferation." (PMID 39273313, 2024).
lupus nephritis (1 paper, 2011). Glomerulonephritis in the context of systemic lupus erythematosus. "Our previous reports with SLE datasets have identified low PON activity as an independent risk factor for SLE and our analysis of PON1 and PON3 SNPs revealed some modest associations with lupus nephritis." (PMID 21223581, 2011).
Pca (1 paper, 2020). "In the present study, PON3 concentrations in patients with PCa were significantly lower compared to healthy individuals and patients with BPH." (PMID 32549522, 2020). "Serum PON3 decreased significantly in the PCa patients in this study compared to the control group." (PMID 32549522, 2020). "PON1 and PON3 levels decreased significantly in patients with PCa, while MDA levels increased." (PMID 32549522, 2020). "PON1 and PON3 increased postoperatively in the PCa group, while MDA decreased." (PMID 32549522, 2020). "The present study compared paraoxonase (PON1, PON3), PON1/HDL, triglyceride, HDL, LDL, and MDA levels in patients with PCa among individuals with BPH, undergoing RARLP, with no biochemical recurrence and a control group." (PMID 32549522, 2020).
prediabetes (1 paper, 2024). "The literature review revealed T2D or prediabetes associations with 10 proteins, including PON3, PLTP, and SHBG." (PMID 39589852, 2024). "PON3 exhibited a sharp decline in participants with T2D or prediabetes at both visits." (PMID 39589852, 2024).
sarcopenia (1 paper, 2024). Progressive decline in muscle mass due to aging which results in decreased functional capacity of muscles. "Further cellular, animal and clinical studies of PON3 are needed for an in-depth understanding of the pathogenesis and mechanism of sarcopenia." (PMID 39725826, 2024). "PON3 is highlighted as a potential biomarker for patients with age-related sarcopenia." (PMID 39725826, 2024). "Decline in PON3 may result in an overload of oxidative stress in skeletal muscles and contribute to sarcopenia." (PMID 39725826, 2024). "We propose that PON3 could be considered as a potential biomarker for age-related sarcopenia and a promising target for intervention." (PMID 39725826, 2024). "PON3 has been identified as a potential novel biomarker for age-related sarcopenia." (PMID 39725826, 2024). "Our study is the first to report the role of PON3 as a biomarker for sarcopenia in aged population." (PMID 39725826, 2024). "PON3 was confirmed to be down-regulated in older adults with sarcopenia, which may lead to sarcopenia due to impaired antioxidant defenses." (PMID 39725826, 2024). "Our study investigated the plasma proteome of individuals with age-related sarcopenia and identified 8 DEPs that showed promising predictive performance, including IGFBP2, PON3, LRG1, PRDX6, PTGDS, CD163, PRG4, and TRAJ17." (PMID 39725826, 2024). "Notably, PON3 was significantly down-regulated in the sarcopenic group, consistent with the DIA analysis, indicating its potential as a biomarker for sarcopenia development." (PMID 39725826, 2024). "IGFBP2 (AUC 0.8756) and PON3 (AUC 0.8344) demonstrated the top 2 AUC values, indicating their decent ability to differentiate individuals with sarcopenia from those without sarcopenia." (PMID 39725826, 2024). "Subsequent ELISA validation in an independent cohort confirmed significantly different expression levels of PON3 and IGFBP2 between individuals with and without sarcopenia." (PMID 39725826, 2024).
sickle cell disease (1 paper, 2019). Sickle cell anemias are chronic hemolytic diseases that may induce three types of acute accidents: severe anemia, severe bacterial infections, and ischemic vasoocclusive accidents (VOA) caused by sickle-shaped red blood cells obstructing small blood vessels and capillaries. "Here, for the first time, we described PON-1 activities and PON-1, PON-2, PON-3 polymorphisms in patients with sickle cell disease, homozygous for HbSS, compared with healthy controls." (PMID 31366068, 2019). "The allele distribution of the PON-1, PON-2, and PON-3 polymorphisms followed the Hardy–Weinberg equilibrium in the sickle cell disease group as well as in the healthy control group." (PMID 31366068, 2019). "Here, for the first time, the arylesterase and paraoxonase activities of PON-1 were evaluated, as well as the frequency of the polymorphism in PON-1, PON-2, and PON-3 genes, in patients with sickle cell disease." (PMID 31366068, 2019).
spinal cord injury (1 paper, 2025). Penetrating and non-penetrating injuries to the spinal cord resulting from traumatic external forces (e.g., WOUNDS, GUNSHOT; WHIPLASH INJURIES; etc.). "This study systematically explores the action mechanism of Pon3 and its regulatory targets in spinal cord injury (SCI)." (PMID 40884250, 2025).
stable angina (1 paper, 2015). "Relative intensity of apoA-I glycation and activities of high-density lipoprotein (HDL)-associated PON1 and PON3 were determined in 205 consecutive T2DM patients with stable angina with (n = 144) or without (n = 61) significant CAD (luminal diameter stenosis ≥ 70 %)." (PMID 25964115, 2015).
Stroke (1 paper, 2013). Sudden impairment of blood flow to a part of the brain due to occlusion or rupture of an artery to the brain. "The absence of any positive correlations between stroke risk and the two PON3 polymorphisms in our study was also consistent with reported findings in Caucasian and North American patients." (PMID 23356507, 2013).